CD27 (CD27 molecule)
Diseases named in the same sentence as CD27 in open-access papers (continued):
Sharing a sentence is not in itself a finding about the gene and the disease.
lymphoma (38 papers, 2012 to 2025). A malignant (clonal) proliferation of B- lymphocytes or T- lymphocytes which involves the lymph nodes, bone marrow and/or extranodal sites. "The interaction between CD70 and CD27 can stimulate the proliferation and survival of cancer cells and increase the level of soluble CD27, which is associated with poor prognosis in patients with lymphoma and certain solid tumors." (PMID 37849799, 2023). "To examine the contribution of mAb isotype to anti-CD27 therapy, we returned to our well-validated lymphoma model and compared m1 or m2a variants of anti-mCD27." (PMID 35288635, 2022). "In a retrospective study, nearly half (11/21) of CD70-deficient and 36% (12/33) of CD27-deficient patients developed lymphomas, with Hodgkin’s lymphoma (HL) being the most common malignancy." (PMID 34638238, 2021). "Although exceedingly rare, human CD27 deficiency has been associated with Epstein-Barr virus (EBV) associated lymphoproliferative disorders [lymphoma and hemophagocytic lymphohistiocytosis (HLH)], and recurrent infections." (PMID 34630390, 2021). "BCL1 lymphoma, which primarily develops in the spleen of recipient mice, is supressed by anti-CD27 mouse IgG1, an isotype that lacks effector function (ADCC and ADCP), consistent with the CD8 T cell stimulatory effects delivered by this isotype." (PMID 37965342, 2023). "As the expression of CD15, CD27, CD45, and CD152 is also associated with lymphoma cell proliferation these CD molecules can be therapeutic targets." (PMID 34696358, 2021). "SS patients demonstrate aberrations in the distribution of B cell subsets, with CD27+ memory B cells being reduced in the circulation and increased in the SGs, while only SS patients with concurrent lymphoma show an increase in circulating CD27+ B cells." (PMID 33255258, 2020). "Specifically, they showed that a clinically relevant agonist anti-human CD27 mAb (an activating CD27 antibody), varlilumab, contributes to the protection against lymphoma in human-CD27 transgenic mice." (PMID 31358815, 2019). "For example, a human anti-CD27 mAb eliminated CD27-expressing lymphoma and leukemia via multiple mechanisms: antibody-dependent cellular cytotoxicity (ADCC) and enhancing co-stimulation of T cells." (PMID 31186046, 2019). "In human CD27 transgenic mice, varlilumab (an CD27 agonist mAb), similarly synergized with PD-L1 blockade in protecting against lymphoma." (PMID 30519541, 2018). "Another attractive therapeutic strategy is the stimulation of CD27 on T cells to reinforce antitumoral immune responses or directly target CD27-expressing tumors, including many lymphoma types." (PMID 29868474, 2018). "Even so CD70 is so far the only known ligand of CD27, CD27 mutations predispose for a much larger spectrum of EBV-associated pathologies, including HLH and different EBV-associated lymphomas, and also increase the mortality of affected individuals." (PMID 29225606, 2017). "In a xenograft models of lymphoma, administration of the humanized anti-CD27 antibody, 1F5, significantly prolonged survival." (PMID 26697006, 2015). "In this study we sought to better characterize the costimulatory properties of varlilumab, the first anti-CD27 mAb to enter clinical trials for treatment of lymphomas and solid tumors." (PMID 26500773, 2015). "Remarkably, only SS patients with lymphoma showed an increase in CD27-expressing B cells, including CD27 (high) plasma blasts." (PMID 23853604, 2013). "Therefore, blocking the CD70/CD27 signaling axis represents a novel approach in lymphoma immunotherapy." (PMID 40078987, 2025). "Our results thus suggested that dual blockade of the CD70/CD27 and PD‐1/PD‐L1 pathways could hamper lymphoma growth in vivo, at least partially through rescue of T‐cell exhaustion." (PMID 36471481, 2022). "In addition, modulation of both anti- and pro-apoptotic proteins, including the Bcl-2 family, has been described to be dependent of the presence of CD70/CD27 on malignant lymphoma cells." (PMID 34991665, 2022).
lymphoma (continued). "CDX-527 was demonstrated to have potent T-cell activation by increasing IL-2 and IFNγ production and anti-tumor activity to CD27-expressing lymphoma cells in an immunodeficient mouse model, with comparable anti-tumor activity to separate CD27 agonizing and PDL1 inhibiting monoclonal antibodies." (PMID 34630390, 2021). "A CD27-targeting mAb (varlilumab) effectively eliminated CD27-expressing lymphoma and leukemia." (PMID 33121189, 2020). "CD70, a ligand of CD27, is expressed on activated T-cells, B-cells, and lymphoma." (PMID 31041299, 2019). "CD27 expression has been observed in almost all types of B cell lymphoma, suggesting that this marker may be an early indicator of lymphoma development in pSS patients." (PMID 23853604, 2013). "Thus, higher CD74 and CD44 expressions mark CD27+ memory B cells compared with CD27- naïve B cells and differ from those of malignant lymphoma B cells overexpressing CD74." (PMID 22404985, 2012). "Additionally, varlilumab (anti-CD27 agonist) has shown the same in a humanized model of lymphoma." (PMID 33520112, 2021). "Moreover, the co-expression of CD70 and CD27 was observed in 39% of lymphoma samples." (PMID 31652572, 2019). "In addition to CD27, mutations in the magnesium transporter MagT1 and the transcription factor NFκB1 compromise NK cell recognition and predispose for EBV-induced lymphoproliferations and lymphomas." (PMID 29225606, 2017). "An early study using a lymphoma model highlighted that in the activation of cytotoxic CD8 + T cells, CD27 signaling played a central role for antitumor response." (PMID 39105866, 2024). "Clinically, the CD27/CD28 co-stimulatory combination yielded impressive responses in neuroblastoma, AML, and lymphoma patients." (PMID 35053463, 2022). "Our analysis found that the Spike-RBD can potentially interact with CD15, CD27, CD45, and CD152 expressed by lymphoma cells." (PMID 34696358, 2021). "Although significantly lower levels of CD20+CD27+CD24+CD40+CXCR4+CXCR5+ B cells were observed in MC14 of HIV+ pre-NHL (cART-naïve) samples, these cells had a potential pre-lymphoma phenotype as they expressed both cMYC and AICDA compared to HIV+ cART-naïve and HIV-negative samples." (PMID 39324141, 2024). "Interestingly, in some tumors, such as lymphoma, expression of CD70 on tumor cells and APCs improved anti-tumor immunity, whereas, in others, this CD27/CD70 signaling led to decreased anti-tumor immunity and increased Treg populations." (PMID 37174089, 2023). "Constitutive CD27 and CD70 expression has also been detected on T cell neoplasia such as anaplastic large cell lymphoma, peripheral T cell lymphoma, cutaneous T cell lymphoma, adult T cell leukemia/lymphoma and extranodal NK/T cell lymphoma." (PMID 34991665, 2022). "In syngeneic colorectal and lymphoma models with little to no expression of CD27, treatment with the 1F5 mAb also elicited antitumor activity and increased survival." (PMID 26697006, 2015). "We previously showed that the proportion of circulating B cells that expressed CD27 was significantly reduced in HIV infection and serum levels of soluble CD27 (sCD27) were significantly elevated in HIV+ subjects who went on to develop AIDS-NHL compared to HIV+ subjects who did not develop lymphoma." (PMID 39324141, 2024). "Finally, in a murine lymphoma model, we demonstrated that blocking the CD70/CD27 and/or PD1/PD‐L1 interactions could reduce CD70+ lymphoma growth in vivo, by directly impairing the tumour cell proliferation and rescuing the exhausted T cells." (PMID 36471481, 2022). "Interestingly, CD27 on malignant B cells triggers CD70 reverse signaling in NK cells, resulting in increased numbers of tumor-infiltrating activated NK cells and prolonged survival of CD27-expressing lymphoma-bearing mice." (PMID 31186046, 2019).
influenza (37 papers, 2010 to 2025). An acute viral infection of the respiratory tract, occurring in isolated cases, in epidemics, or in pandemics; it is caused by serologically different strains of viruses (influenzaviruses) designated A, B, and C, has a 3-day incubation period, and usually lasts for 3 to 10 days. "Another study reported that age-related inefficiency of a trivalent influenza vaccine response was associated with lower frequencies of transitional (IgD+CD27+/-CD38+/-), class-switched memory (SwM), and double-negative (DN) B cells." (PMID 39613759, 2024). "C6 MBCs are also CD21+ and similar to a stable pool of CD27− MBCs that are generated in response to new influenza variants." (PMID 35759653, 2022). "In humans, it was shown that an increased level of CD27+ ABCs in the blood of the elderly was associated with a low titre of influenza antibodies." (PMID 34206312, 2021). "Such impairment, persisting long after treatment discontinuation, is linked to a severe depletion of CD27+ memory B-cells that directly correlates with low IgM levels and impaired response to influenza vaccines." (PMID 34078415, 2021). "It was shown that an increased level of CD27 + ABCs in the blood of the elderly was associated with a reduced titer of influenza-specific antibodies." (PMID 34696233, 2021). "This is consistent with studies showing that CD27low cells are more susceptible to apoptosis and that accumulation of influenza-specific T lymphocytes was impaired in the lungs of Cd27−/− mice during infection." (PMID 24130498, 2013). "CD40 L and IFNγ levels were detected after stimulating Tfh cells with an influenza antigen; the positive rates of CD27 and CD38 in B cells were detected before and after coculture with Tfh cells." (PMID 35494526, 2022). "Our data show that after influenza infection CD27+CD11b+ effector NK cells appear in the alveolar space and lung tissue of WT mice but not in Il27ra−/− mice, suggesting a critical role for IL-27 in regulating this NK subset." (PMID 30899058, 2019). "Peripheral blood plasmablasts (CD19 + IgD-CD38 + CD27++) were single cell sorted from a healthy subject seven days after immunization with the 2014–2015 seasonal inactivated quadrivalent influenza vaccine." (PMID 29531320, 2018). "CD27+ memory B-cells, and especially resting memory B-cells, are responsible for generating antibody responses, and circulating influenza-specific memory B-cells can last for decades." (PMID 28693586, 2017). "In line with the different studies investigating biomarkers for influenza and hepatitis B vaccine responses in the elderly, we observed trends toward lower numbers of switched memory CD27+ B cells in the low responders." (PMID 29375578, 2017). "In the absence of significant changes in other NK cell markers (CD45RO, NKp44, CXCR6, CD57, NKG2C, CCR7, CD62L and CD27), influenza vaccines induced memory NK cells with the distinct feature of intracellular NKp46 expression." (PMID 25781472, 2015). "We also observed an inverse correlation between the overall frequencies of IgD+CD27- B cells and influenza-specific B cell ELISPOT response measures at different timepoints relative to vaccination." (PMID 25816015, 2015). "In severe influenza CD8 activation peaked more than 9 days post-onset, and/or was excessive (30–90% HLADR+CD38+) in association with accumulation of CD27+CD28− cells and maintenance of CD8 counts." (PMID 22363665, 2012). "The last wave of influenza-specific T cells expressed CD27, suggesting expansion from a less differentiated memory T cell pool." (PMID 22132212, 2011). "Together, our results show influenza-derived GFL9/HLA-A2-restricted CD45RA+CD27− effector T cells express lower levels of CD28 compared to that of CD45RA−CD27+ memory T cells." (PMID 20844584, 2010). "Notably, influenza infection amplified these immunological shifts, particularly in CD27+ memory B cell depletion during advanced pregnancy stages." (PMID 40558593, 2025).
influenza (continued). "Thus far, post‐vaccination changes in numbers of circulating follicular (CXCR5+) CD4+ T cells and plasmablasts (CD19 + CD27 + CD38+) at day 7 were described as some of the best correlates of antibody responses to influenza vaccination." (PMID 38146131, 2024). "Interestingly, several studies reported an increased percentage of Ag-specific CD27+CD21-/dim B cells 14 days after influenza vaccination." (PMID 35214595, 2022). "Abnormalities in IL-15, NCR1, CD27, and an increase in T & NK cell activation traits, similar to those observed during swine flu and influenza, were prominent and may be considered a target of further investigation using a more controlled methodology." (PMID 34177897, 2021). "Studies have also shown that, following influenza vaccination, HIV+ individuals have higher frequencies of B cells expressing the inhibitory receptor FcrL4) and markers of exhaustion or senescence (IgD− CD27−) that are associated with low antibody titres." (PMID 36845567, 2021). "Utilizing a model of influenza infection, an early study indicated that CD27 and to a lesser extend 4-1BB (CD137) are essential during initial priming of virus-specific cytotoxic CD8+ T cells, whereas the formation of memory was dependent on CD27, 4-1BB, and OX40." (PMID 32674488, 2020). "We defined memory subsets within influenza-specific A2/M158+CD8+ T cells across the human lifespan, namely Tnaïve (CD27+CD45RA+CD95-), Tscm (CD27+CD45RA+CD95+), Tcm (CD27+CD45RA-), Tem (CD27-CD45RA-), and Temra (CD27-CD45RA+) subsets, ex vivo." (PMID 40694338, 2025). "Here it is revealed that the costimulatory receptors CD27 and ICOS coordinately sustain PD-1high CD8+ TRM cell populations following resolution of acute influenza infection." (PMID 41262009, 2025). "In general, among influenza+ patients, tetramer+CD8+ T cells consisted of central memory-like (Tcm, CD27+CD45RA–) and, to a lesser extent, effector memory-like (Tem, CD27–CD45RA–) phenotypes, while tetramer+CD4+ T cells were predominantly of Tcm-like cells." (PMID 33976217, 2021). "Several studies have investigated the effect of influenza vaccines on T cell populations, demonstrating that LAIV increases peripheral blood memory T cells in children, but decreases CD8+CD27+ T cells in adults 10 days post inoculation." (PMID 26820305, 2016). "Of the proteins with reduced expression identified in our study, the five most-reduced DEPs in samples from influenza-infected patients that were also correlated with higher viral loads were CTSD, KLK7, MFGE8, MAPK9 and CD27, respectively." (PMID 27088501, 2016). "In the longitudinal samples, we observed differential kinetics of expansion for influenza-specific CD8 T cell memory responses delineated on the basis of their expression of two surface markers, CD45RA and CD27." (PMID 22132212, 2011). "Similarly, analysis of CD27/CD45RA/CD95 phenotypes showed significant differences in the activation of tetramer+ CD8+ and CD4+ T cells in influenza+ patients when compared to the parental CD8+ and CD4+ T cell populations at acute and follow-up timepoints." (PMID 33976217, 2021). "cTfh cells share phenotypic and functional properties to GC Tfh cells, and it has been shown that inactivated influenza vaccination (IIV) induces expansion and PD-1/ICOS-activation of CD4+CXCR5+CXCR3+ cTfh type-1 (cTfh1) cells, which correlated with antibody and CD19+CD27++CD38++ ASC responses." (PMID 33976217, 2021). "We found a significant reduction in the percentages of CD27+CD11b+ NK cell effector population in the alveolar space of Il27ra−/− but not WT in influenza-infected mice." (PMID 30899058, 2019). "CD8 activation peaked 6–8 days after mild influenza onset, when 13% (6–22%) were HLADR+CD38+, and was accompanied by a significant loss of resting/CD27+CD28+ cells without accumulation of CD27+CD28− or CD27−CD28− cells." (PMID 22363665, 2012).
influenza (continued). "In our study, in the influenza-specific CD8+ T cells there was not a predominant population based on CD27 and CD28 expression." (PMID 22920436, 2012). "Most influenza reactive T cells from the young donors express both CD28 and CD27 on their surface." (PMID 21887299, 2011). "We found a higher proportion of the influenza responsive CD8 and CD4 T cells were of this late effector CD45RA+ phenotype, and that CD8 but not CD4 T cells had also significantly lost expression of costimulatory molecules CD28 and CD27." (PMID 21887299, 2011).